H19 (H19 imprinted maternally expressed transcript)
Diseases named in the same sentence as H19 in open-access papers (continued):
Sharing a sentence is not in itself a finding about the gene and the disease.
tumor (continued). "Since H19`s expression is epigenetically controlled and LOI of H19 has been found in some tumor types, we determined allelic expression of H19 in human HCC by RFLP analysis employing the 32 samples from our patient cohort." (PMID 31225433, 2017). "Some lncRNAs, such as HOTAIR, H19, NEAT1, HNF1A-AS, ANRIL, are reported to be oncogenic molecules in NPC, while GAS and MEG3 lncRNAs act as tumor suppressors." (PMID 28467811, 2017). "The mice injected with shH19 cells formed apparently smaller tumor mass than the mice injected with NTC cells, indicating that H19 was critical for tumor growth." (PMID 28102845, 2017). "We also highlighted common long non-coding RNA molecules such as HULC, HOTAIR, MALAT1, XIST, H19 and GAS5, which mediate the two-way interactions between stroma and tumor." (PMID 28392501, 2017). "Expression of the seven lncRNAs UCA1, MALAT1, H19, GAS5, TUG1, ncRAN (SNHG16) and linc-UBC1 (BLACAT) was measured by RT-qPCR in UC tissue set 1 consisting of 106 tumor tissues and 10 benign tissues obtained from radical cystectomies." (PMID 28430799, 2017). "Up-regulation of H19 has been confirmed in undifferentiated NPC biopsies and LSCC tumor tissues and is related to low LSCC survival rates and cancer progression." (PMID 27802187, 2017). "Previous research identified that over-expression of H19 in CD133+ GBM cells increased their neurosphere formation and tumor growth, which showed the importance of H19 in GSCs." (PMID 26983719, 2016). "The correlation between imprinting defects at 14q32-DMRs and H19-DMR was 0.78 (R2 = 0.61), potentially implicating both loci in tumor development." (PMID 26802029, 2016). "Through several algorithms, researchers found miR-675 regulated cell proliferation of GC cells by targeting the tumor suppression gene Runt Domain Transcription Factor 1 (RUNX1) and consisted of the H19/miR675/RUNX1 axis pathway." (PMID 27143813, 2016). "At the same time, H19 expression, TNM stage and tumor differentiation was also significantly correlated with OS in our study cohort (P = 0.006, P = 0.008, P = 0.006, respectively)." (PMID 26989025, 2016). "When the tumor cells settle at the secondary site, the EMT inducing environmental signals will be absent and this will weaken and break the loop between Slug and H19, and thus contribute to the reversion to MET and the up-regulation of E-cadherin." (PMID 26623562, 2016). "H19 was knocked down in several GBM cell lines, after which the cell proliferation rate, apoptosis, tumor formation capability, and expression of CSC markers were measured." (PMID 26983719, 2016). "By exploring the expression of the competing triplets H19-miR-206-PAX3, we also found that the correlations between miR-206 with the two ceRNAs (H19 and PAX3) were all positive in normal and tumor states." (PMID 27580177, 2016). "For example, H19 can promote EMT progression and accelerate tumor growth by acting as competing endogenous RNA (ceRNA) for miR-138 and miR-200a in CRC." (PMID 26637808, 2016). "At the same time, another partner of H19, PAX3 interact with a new ceRNA RP11-356J5.12.1 in tumor state." (PMID 27580177, 2016). "The results demonstrated that H19 was upregulated in CRC tissues in comparison with adjacent normal colon tissue and that H19 upregulation correlated with tumor differentiation and TNM stage." (PMID 26989025, 2016). "Tumor size increased 2-fold in rats that underwent 70% hepatectomy compared to sham operated animals with an increase of both HGF and H19 RNAs." (PMID 26623562, 2016). "In the normal state, H19 compete with ZEB1 and PAX3, while the interaction between H19 and ZEB1 is ‘switch off’ in the tumor." (PMID 27580177, 2016). "Among them, HOTAIR, PVT1, H19, MALAT1, GHET1 and HULC were significantly higher in tumor tissues compared with control tissues." (PMID 26096073, 2015).
tumor (continued). "Stable expression of H19 significantly promotes EMT progression and accelerates in vivo and in vitro tumor growth." (PMID 26068968, 2015). "These subpopulations were found to possess different patterns of lncRNA expression, such as the upregulations of H19, XIST and MIAT in undifferentiated tumor cells." (PMID 26230711, 2015). "H19 opposite tumor suppressor (HOTS), a protein coded by the H19 antisense transcript and that has tumor suppressor activity has been described recently." (PMID 25884481, 2015). "Several of the detected differentially expressed lncRNAs were well described members of cancer-related pathways, including tumor suppressors and oncogenes (e.g. MEG3, Xist, MALAT1, H19, GAS5, and HOTAIR)." (PMID 25264628, 2014). "The H19 expression is known to be frequently up-regulated in cancer including HCC, acting in different models either as a tumor suppressor, or as an oncogene; its role in hepatocarcinogenesis is still debated." (PMID 25401338, 2014). "In our OS patient’s tumour tissue, the mRNA expression of both IGF2 and H19 has increased significantly (FDR = 3.46E-15 and FDR = 0.0015, respectively)." (PMID 25496518, 2014). "The following DMRs showed aberrant methylation in only one tumor: ARH1-CG1, NAP1L5-DMR, PEG10-DMR, H19 promoter, WT1-AS-DMR, MEG3-CG7-DMR, MCTS2-DMR, NESP-DMR, and GNAS1A-DMR." (PMID 24373183, 2013). "In the present study, combined expression of adenoviral vectors (Ad-EGFP and Ad-E1A) driven by H19 enhancer-DMD-H19 promoter complex was investigated and their effects on the tumor growth were assessed in vitro and in vivo." (PMID 23900345, 2013). "The therapeutic potential of the H19-DTA vector was tested in a rat animal tumor model for colorectal liver metastases, showing tumor growth inhibition in the H19-DTA-treated group as compared to the control group." (PMID 23984081, 2013). "Thus, our observation that H19 can simultaneously induce proliferation and apoptosis highlights a putative dual role of H19 in choriocarcinoma cell lines and may explain the debate over whether H19 is a tumor suppressor or a tumor promotor in trophoblast tissue." (PMID 23711233, 2013). "The SHH ligand gene and Gli-inducible target genes (FOXM1, IGF2, OSF2, H19, and SPP1) were overexpressed in tumour samples as compared with normal bladder tissue." (PMID 22361633, 2012). "Among these, we found some tumor suppressor genes (e.g. H19, ACTN4) that were down-regulated and some genes related to tumor progression and metastasis formation (e.g. ENPP2, GRIA3, TPM3) that were up-regulated." (PMID 23049808, 2012). "Five target genes were significantly overexpressed in the tumour samples compared with normal bladder tissue: FOXM1, IGF2, OSF2, and H19, which promote cell proliferation and growth, and SPP1, which is involved in extracellular matrix interactions." (PMID 22361633, 2012). "By selective killing of cancer cells, which express H19 and IGF2, the treated tumor cells as well as the neighboring tumor cells (as IGF2 mediate its effect in autocrine/paracrine manner) are at least partly deprived of their IGF2 supply." (PMID 21162716, 2010). "H19 is a paternally-imprinted, oncofetal gene that encodes a RNA (with no protein product) acting as a "riboregulator", which is expressed at substantial levels in embryonic tissues, in different human tumor types, and marginally or not expressed in the corresponding tissues of the adult." (PMID 21162716, 2010). "Biallelic and monoallelic IGF2 expressions correlated with hypermethylation and normal methylation of H19 DMR, respectively, in two tumours with LOI and seven tumours with ROI." (PMID 19034281, 2008). "Quantitative RT–PCR analysis showed minimal expression of H19 mRNA and substantial expression of IGF2 mRNA in tumours with LOH or LOI, and substantial expression of both H19 and IGF2 mRNAs in tumours with ROI." (PMID 19034281, 2008).
tumor (continued). "Quantitative real-time reverse transcription-PCR analysis showed that although 15 of 20 tumours had a higher level of IGF2 mRNA than normal liver tissues, 15 of 20 tumours had a lower level of H19 mRNA than normal liver tissues." (PMID 19034281, 2008). "To further assess the expression of H19 in HCC, we determined the level of H19 RNA in a panel of HCC human tumor cell lines." (PMID 17786216, 2007). "H19 expression was significantly higher in tumor vs. non-tumor tissue before treatment and demonstrated moderate potential to discriminate between tumor and non-tumor." (PMID 41751809, 2026). "Multivariate analysis showed advanced patient age (p < 0.001) and large tumor size (p = 0.002) as independent predictors of worse overall survival, irrespective of H19 expression (HR: 0.655; 95% CI: 0.367–1.170; p = 0.153)." (PMID 41521159, 2026). "Furthermore, H19 binds competitively to miR-29b-3p, leading to an increased expression of progranulin, which in turn promotes EMT and contributes to tumor progression." (PMID 40723840, 2025). "Consequently, elevated H19 levels facilitate cancer progression through the disinhibition of LIMK1, contributing to tumor advancement." (PMID 40781643, 2025). "Multiple lncRNAs regulate VEGF expression in tumor cells under various conditions, including Testis Development-Related Gene 1 (TDRG1), MEG3, H19, SNHG1, Non-Coding RNA Activated by DNA Damage (NORAD), Antisense Non-Coding RNA in the INK4 locus (ANRIL), and MALAT1." (PMID 40429961, 2025). "H19 was also increased by short-term DOX induction (although only about 2-fold versus the >100-fold increase in the long-term DOX induced tumor samples) (data not shown), indicating that ERG is inducing H19." (PMID 41321318, 2025). "H19 imprinted maternally expressed transcript (H19) is located on the human 11p15.5 chromosome and is imprinted with the adjacent insulin‐like growth factor (IGF) 2 gene, a tumor suppressor with abnormal expression in various tumor tissues." (PMID 40066229, 2025). "Moreover, H19 inhibits apoptosis in NSCLC cells by regulating multiple signaling pathways and epigenetic mechanisms, solidifying its essential role in tumor survival and resistance to drugs." (PMID 40723840, 2025). "In contrast, the sh-H19 + pcDNA-BMP2 group showed no significant abnormal increase in tumor volume or mass." (PMID 40297808, 2025). "Moreover, H19 is also overexpressed in cancer stem cells in HCC and is promising as a biomarker for this tumor." (PMID 39682684, 2024). "For example, H19, upon transfer from CAFs to lung cancer cells, recruits the DNMT1 enzyme, leading to increased methylation and subsequent suppression of miR-497 expression, a strategy that enhances the tumor cells’ drug resistance." (PMID 39717771, 2024). "Furthermore, H19 partakes in the remodeling of the ECM, altering the tumor microenvironment’s physical landscape to favor tumor cell invasion and metastasis." (PMID 39286016, 2024). "According to previous studies, H19 inhibition using shRNA, siRNA, CRISPR/Cas9 system, and site-specific ASOs may suppress tumor growth, metastasis, and invasiveness." (PMID 38355574, 2024). "Additionally, overexpression of H19 in CD133+ GSCs enhances neurosphere formation and tumor growth, suggesting its role in GSC maintenance." (PMID 39015773, 2024). "Furthermore, several cancer-promoting or tumor-suppressing lncRNAs, such as NEAT1, H19, NRON, LUCAT1, and HOTAIR, can be found not only in malignant cells but also in tumor-specific immune cells." (PMID 36911393, 2023). "Notably, as observed in the H19/let-7 interaction, downregulation of SNHG7 releases miR-3127 (which acts as a tumor suppressor) from its sequestration, increasing its expression and bioavailability." (PMID 38004379, 2023).
tumor (continued). "In this respect, H19 may control cell proliferation, apoptosis, EMT, tumor progression, metastasis, and drug resistance, suggesting its important role in the lncRNA–miRNA–mRNA network in cancer." (PMID 37175800, 2023). "We conducted qRT-PCR for testing lncRNA H19, miR-194, and E2F3 levels in the formed tumor tissues." (PMID 37253635, 2023). "They found that H19 may function as a ceRNA to regulate HER2 expression by sequestering miRNA let-7c, which as a tumor suppressor negatively correlates with the expression of HER2." (PMID 37175800, 2023). "Moreover, the authors demonstrated that the high H19 group GC patients showed higher invasion depth, advanced TNM (tumor, nodus and metastases) stage and regional lymph nodes metastases than the lower H19 expression group GC patients." (PMID 37179825, 2023). "Moreover, H19 is involved in the STAT3 pathway, which is critical for cancer aggressiveness, potentially impacting the tumor microenvironment." (PMID 37760852, 2023). "At surgery, RNAscope in situ hybridization of IGF2 and H19 revealed the presence of 14% of mosaic cells in one FFPE non-tumor slide but not in the frozen sample." (PMID 37932266, 2023). "One may speculate that a complete knockout of UHMK1 or H19, e.g. by the use of CRISPR/Cas would have resulted in an even more pronounced inhibition of tumor xenograft growth." (PMID 35359403, 2022). "Next-generation sequencing as well as microarray analysis have identified recurrent deregulated lncRNAs (e.g., MALAT1, H19, HOTAIR, ANRIL) across different cancer types that affect tumor-driving processes including proliferation, survival, migration or genomic stability." (PMID 35454868, 2022). "In addition, lincRNA-p21 has been described as a tumor suppressor, while HOTAIR, MALAT-1, H19, PVT1, ANRIL, and GIHCG, have been characterized as oncogenic lncRNAs." (PMID 36360316, 2022). "Differential expression analysis revealed significant divergence in lncRNA profile between parental tumors and tumor-derived cell cultures in vitro, including the following particles: MALAT1, CASC2, H19, TUSC7, XIST, RP11-838N2.4, DLX6-AS1, GLIDR, MIR210HG, SOX2-OT." (PMID 33245508, 2022). "According to RNA-FISH experiments, H19 expression was localised in tumour stroma rather than the tumour itself." (PMID 36358867, 2022). "It has been demonstrated that hypoxia could induce the aberrant expression of lncRNAs, such as H19, HOTAIR, and NEAT1 to regulate tumor biology." (PMID 35846431, 2022). "Besides, by constructing Over H19‐Propofol‐Huh7‐exo mouse model, researchers found the high level exsomal lncRNA H19 promote the growth and metastasis of HCC tumors, hence verifying propofol’s anti-tumor effect conversely." (PMID 36713494, 2022). "The results demonstrated that the expression of anti‐tumour lncRNAs DICER‐AS1, TUG1, GAS5 and LINC01121 was significantly increased by 50 μM resveratrol in combination with H19 knockdown, while expression of MALAT1 in cells was significantly downregulated by the combined treatment." (PMID 35166018, 2022). "H19 is expressed higher in EC and tumor tissues than in the normal endometrial epithelium, and it regulates migration and invasion of the tumor cells." (PMID 35103065, 2022). "H19, a direct transcriptional target of MYC, was shown to be up‐regulated in NSCLC tumour tissues." (PMID 33237626, 2021). "H19 can act as a competing endogenous RNA of miR-370-3p, resulting in the promotion of TGFB1-induced EMT, and as an inhibitor of a tumor-suppressor miRNA let-7, resulting in increased tumor cell migration and invasion." (PMID 34680193, 2021). "H19 and miR-675 have been shown to be elevated in many cancers, including inflammation-induced HCC, but their roles in cancer are controversial, with some researchers suggesting tumor suppressor activity and others demonstrating pro-tumorigenic activity." (PMID 33499244, 2021).
tumor (continued). "In the same manner, the lncRNA H19 and hepatocyte nuclear factor 1A-antisense RNA (HNF1A-AS) are overexpressed in NPC tissues and involved in the modulation of cell cycle progression, tumor cell proliferation, migration and epithelial to mesenchymal transition (EMT)." (PMID 34576322, 2021). "Thus, it is plausible that H19 induces acquired MDR in CRC patients, largely via its effect on mediating tumor apoptosis and migration." (PMID 33402118, 2021). "H19 lncRNA was first described as a parentally imprinted lncRNA expressed from the IGF2 (insulin-like growth factor 2) locus that plays a role in fetal growth and tumor etiology, in part by controlling DNA methylation." (PMID 34316694, 2021). "There is a selection of cells expressing high levels of H19 during the microevolution of tumor progression, which suggests that this lncRNA does not act as a tumor-suppressor." (PMID 34680193, 2021). "The imprinted H19 long non-coding RNA, a knowing oncofetal gene, presents a controversial role during the carcinogenesis process since its tumor suppressor or oncogenic activity is not completely elucidated." (PMID 34526543, 2021). "LncRNA H19, HOTAIR, and MVIH mainly regulate the proliferation, migration, invasion and angiogenesis of tumor cells by regulating VEGF, VASH2, and miR138/HIF1α axis." (PMID 34616746, 2021). "When lncRNA-NC (group A), H19-sh (group B), and H19-sh+PI3K-inhibition (group C) were subcutaneously injected into the nude mice, the tumor volume and mass of nude mice in group B increased greatly (P < 0.050), and the tumor volume and mass in group C were lower than group A (P > 0.05)." (PMID 34250088, 2021). "Next, we confirmed a function of APOBEC3G in cancer progression, because sulforaphane or H19 knockdown subsequently decreased the expression of APOBEC3G, and APOBEC3G siRNA reduced cell viability, migration, invasion and tumor xenograft growth in our PDAC models." (PMID 33669381, 2021). "We bioinformatically selected H19 candidate target genes and have chosen APOBEC3G as the top candidate gene due to its statistically relevant high correlation and a suggested interesting biological function as a virus-induced tumor promoter." (PMID 33669381, 2021). "Here, we summarize ncRNAs with tumor-promoting functions: HOTAIR, HOTTIP, MALAT1, lncRNA H19, lncRNA PVT1, circ-RNA ciRS-7, circ-0030235, circ-RNA_100782, circ-LDLRAD3, circ-0007534, circRHOT1, circZMYM2, circ-IARS, circ-RNA PDE8A, miR-21, miR-155, miR-221/222, miR-196b, miR-10a." (PMID 32257946, 2020). "CAFs promote stemness and chemotherapy (oxaliplatin) resistance in CRC cells through the transfer of exosomal lncRNA H19; lncRNA H19 acts as an endogenous sponge for miR-141, de-repressing the B-catenin pathway; in vivo, CAF-derived exosomes promoted tumor growth." (PMID 32957712, 2020). "Similarly, lncRNA H19 is significantly up-regulated in CAF-derived exosomes in colorectal cancer and acts as a competing endogenous RNA sponge to tumor suppressive miR-141." (PMID 32957712, 2020). "Methylated H19 RNA may compete with MYC mRNA for binding to G3BP1, promoting tumor cell progression." (PMID 32978516, 2020). "The speculated mechanism of which is that H19 potentiates the expression of HMGA2 (high mobility group AT-hook 2), a key regulator of tumor metastasis, by targeting let-7." (PMID 33520725, 2020). "H19 knockdown significantly inhibited tumor growth, and, in some cases, tumors did not form at all, suggesting an oncogenic role for H19 in HCC." (PMID 32429417, 2020). "In vivo models suggest that H19 is a tumor suppressor in hepatocarcinogenesis rather than an oncogene." (PMID 32429417, 2020). "BC-819 can be concentrated most in tumor tissues that upregulate lncRNA H19 rather than in para-tumor tissues, and then subsequent transcription of the diphtheria toxin A gene can generate a cell killing effect." (PMID 32973402, 2020).